SRP54 (signal recognition particle 54)
Description:
Component of the signal recognition particle (SRP) complex, a ribonucleoprotein complex that mediates the cotranslational targeting of secretory and membrane proteins to the endoplasmic reticulum (ER). As part of the SRP complex, associates with the SRP receptor (SR) component SRPRA to target secretory proteins to the endoplasmic reticulum membrane. Binds to the signal sequence of presecretory proteins when they emerge from the ribosomes. Displays basal GTPase activity, and stimulates reciprocal GTPase activation of the SR subunit SRPRA. Forms a guanosine 5'-triphosphate (GTP)-dependent complex with the SR subunit SRPRA. SR compaction and GTPase mediated rearrangement of SR drive SRP-mediated cotranslational protein translocation into the ER. Requires the presence of SRP9/SRP14 and/or SRP19 to stably interact with RNA (By similarity). Plays a role in proliferation and differentiation of granulocytic cells, neutrophils migration capacity and exocrine pancreas development.
Synonyms: SCN8
Tractability: Small molecule: a structure with a bound ligand is known. PROTAC: ubiquitination databases record sites on it; its protein half-life has been measured.
Gene: Protein-coding gene on chromosome 14 (34,981,957 to 35,029,686, forward strand). Ensembl gene ENSG00000100883.
Subcellular location: Nucleus speckle; Cytoplasm; Endoplasmic reticulum
Subcellular location (Human Protein Atlas): Cytosol
Pathways (Reactome):
Metabolism of proteins: SRP-dependent cotranslational protein targeting to membrane
Gene Ontology:
Molecular function: 7S RNA binding; endoplasmic reticulum signal peptide binding; GDP binding; GTP binding; GTPase activity; protein binding; ribonucleoprotein complex binding; RNA binding
Biological process: granulocyte differentiation; protein targeting to ER; exocrine pancreas development; neutrophil chemotaxis; SRP-dependent cotranslational protein targeting to membrane; SRP-dependent cotranslational protein targeting to membrane, signal sequence recognition; SRP-dependent cotranslational protein targeting to membrane, translocation
Cellular component: cytoplasm; endoplasmic reticulum; nuclear speck; nucleolus; nucleus; signal recognition particle, endoplasmic reticulum targeting; cytosol; signal recognition particle
Genetic constraint (gnomAD): Loss-of-function variants: 6 observed, 38.95 expected, observed/expected ratio (o/e) 0.15, 90% interval 0.083 to 0.3. The upper end of that interval is the gene's LOEUF score, 0.3, which puts it in group 1 of 6, group 1 being the genes least tolerant of losing a copy. Missense variants: 229 observed, 446.12 expected, observed/expected ratio (o/e) 0.51, 90% interval 0.46 to 0.57. Synonymous variants: 129 observed, 132.9 expected, observed/expected ratio (o/e) 0.97, 90% interval 0.84 to 1.12.
Homologues: Orthologues: chimpanzee FAM177A1 (100% identical), dog SRP54 (100% identical), macaque SRP54 (100% identical), pig SRP54 (100% identical), mouse Srp54a (99% identical), mouse Srp54b (99% identical), guinea pig SRP54 (99% identical), rat Srp54a (99% identical), mouse Srp54c (99% identical), rabbit SRP54 (97% identical), tropical clawed frog srp54 (97% identical), zebrafish srp54 (96% identical), and 2 more. Paralogues in human: SRPRA (15% identical).
Diseases named in the same sentence as SRP54 in open-access papers:
SRP54 is named in the same sentence as 27 diseases in open-access papers, as found by Europe PMC text mining. Sharing a sentence is not in itself a finding about the gene and the disease. The quoted sentences say what the papers report.
neutropenia (11 papers, 2019 to 2025). A decrease in the number of neutrophils found in the blood. "Patients with SRP54 heterozygous mutations exhibit neutropenia (low number of neutrophils), transient moderate anemia, frequent infections, and skeletal abnormalities." (PMID 35754847, 2022). "Autosomal dominant mutations in SRP54 are known from three different patients and result in neutropenia with similarities to the Shwachman-Diamond Syndrome." (PMID 35008565, 2021). "In fact, mutations in SRP54 are the second most common cause of severe inherited neutropenia in the French Congenital Neutropenia Registry." (PMID 34113652, 2021). "In two of the three patients, their neutropenia, due to the SRP54 mutation, was also accompanied by an exocrine pancreatic insufficiency." (PMID 35008565, 2021). "The heterogenic phenotypes of SDS-like disease and mild to severe neutropenia observed in patients with SRP54 variants may be the result of the effect that mutant SRP54 proteins exert on downstream XBP1 splicing in a dominant-negative manner." (PMID 41383606, 2025). "Among them, SRP54 is associated with the autosomal dominant form of neutropenia (MIM# 618752)." (PMID 37260775, 2023). "Point mutations in SRP54 are associated with severe neutropenia and Shwachmann–Diamond syndrome-like symptoms, which affect development and function of tissues with high secretory activity, such as the pancreas, as well as skeletal and neurodevelopmental defects." (PMID 35409131, 2022). "Using this criterion, we did not detect EIF6 mutations in the 15 healthy controls, the 5 SDS patients post-HSCT, the 5 patients with neutropenia of unknown molecular origin, or the SRP54-deficient patient." (PMID 34413298, 2021). "An srp54-knockdown zebrafish model was established by Carapito and Konantz and colleagues that revealed that suppression of srp54 induces neutropenia and exocrine pancreas defects in zebrafish embryos (see poster: Bone marrow failure syndromes)." (PMID 31519693, 2019). "Nearly all reported patients with SRP54 mutations had neutropenia without a cyclic pattern and showed a poor or no response to granulocyte colony-stimulating factor (G-CSF) therapy." (PMID 36159802, 2022). "SRP54 mutations are not restricted to SDS patients and could be involved in the generic mechanism of neutropenia." (PMID 34113652, 2021).
myositis (5 papers, 2006 to 2023). "Autoantibodies recognizing SRP54, a myositis-associated autoantigen, increased by over 4-fold between the first and second time points in individual AA19 who also carried anti–PDC-E2 and anti–TPO CTD-AAbs at baseline." (PMID 36752204, 2023). "It is unknown whether a subset of patients with autoantibodies present early in the course of disease will go on to develop CTD autoantibody–associated clinical manifestations such as myositis (e.g., anti-SRP54) or thyroiditis (anti-TPO)." (PMID 36752204, 2023). "Anti-SRP54 is associated with immune-mediated necrotizing myopathy (IMNM) and is a recognized biomarker for myositis." (PMID 36752204, 2023). "In myositis-panel analyses, positivity for SRP54-Ab was detected and therapy with pulsed methylprednisolone intravenous (IV) in combination with oral prednisolone and methotrexate was started." (PMID 34572153, 2021). "The role of anti-SRP54 in myositis and how anti-SRP54 may be induced during infection, however, remains unknown." (PMID 36752204, 2023). "The disease control samples (including those with myositis, myasthenia gravis and Duchenne muscular dystrophy) were all negative for anti-SRP54 antibody." (PMID 25963141, 2015).
congenital neutropenia (4 papers, 2019 to 2022). "SRP54 mutations have recently been implicated in congenital neutropenia (CN) and the in‐frame deletion, p.Thr117del, is the most common pathogenic mutation reported." (PMID 35846055, 2022). "The SRP54 gene encodes signal recognition particle (SRP) 54 GTPase protein and mutations in SRP54 have been linked to congenital neutropenia (CN) and a Schwachman‐Diamond‐like syndrome." (PMID 35846055, 2022). "This group includes congenital neutropenia caused by mutations in ELANE, GFI1, HAX1, WAS (X-linked neutropenia), CSF3R, and SRP54 genes." (PMID 31709206, 2019).
bone marrow failure syndrome (2 papers, 2019 to 2022). "Likewise, the qPCR validated SRP54 gene has been linked to bone marrow failure syndromes and skeletal abnormalities." (PMID 35151275, 2022).
influenza (2 papers, 2023 to 2024). An acute viral infection of the respiratory tract, occurring in isolated cases, in epidemics, or in pandemics; it is caused by serologically different strains of viruses (influenzaviruses) designated A, B, and C, has a 3-day incubation period, and usually lasts for 3 to 10 days. "In line with ZIKV infection, SRP54 depletion significantly reduced influenza viral titres." (PMID 39621795, 2024). "Autoantibodies including anti-SRP54 and anti-TPO developed in 2 patients with influenza and remained elevated approximately 1 month after their first hospital visit, suggesting that viral infection triggered autoantibody development." (PMID 36752204, 2023). "Molecular mimicry is also unlikely to explain the development of anti-SRP54 and anti-TPO in influenza and SARS-CoV-2 infection, as this mechanism would imply that self-proteins cross-react with proteins from 2 unrelated respiratory viruses." (PMID 36752204, 2023).
viral infection (2 papers, 2023 to 2024). "To verify the role of the SRP and SR in live virus infection, we infected the SRα, SRβ and SRP54 depleted HeLa cells with ZIKV at MOI 0.1." (PMID 39621795, 2024).
acute myeloid leukemia (1 paper, 2022). Acute myeloid leukemia (AML) is a group of neoplasms arising from precursor cells committed to the myeloid cell-line differentiation. "A 15‐year‐old male with SRP54‐mutated CN (p.Thr117del) was diagnosed with acute myeloid leukemia with myelodysplasia‐related changes on a screening bone marrow evaluation." (PMID 35846055, 2022).
agranulocytosis (1 paper, 2025). "The next group included seven families with heterozygous changes in SRP54, five of which were recurrent in-frame p.Thr117 deletion and seemed to be associated with agranulocytosis." (PMID 41383606, 2025).
autoimmune disease (1 paper, 2021). A disorder resulting from loss of function or tissue destruction of an organ or multiple organs, arising from humoral or cellular immune responses of the individual to their own tissue constituents. "Of note, although not based on mutations in the SRP54 gene, auto-antibodies directed against the SRP54 protein are considered as diagnostic biomarkers as well as pathogenic agents driving the progression of immune-mediated necrotizing myopathy, a muscle-specific autoimmune disease." (PMID 35008565, 2021).
bipolar affective disorder (1 paper, 2021). "Srp54 gene expression was strongly down-regulated in response to anti-inflammatory and anti-depressant drugs and a single nucleotide polymorphism (SNP) in Srp54 has been associated with bipolar affective disorder." (PMID 34113652, 2021). "The role of SRP19 and SRP54 in neuronal diseases, such as bipolar affective disorder and neuroticism, need to be eluciated and warrant future investigation." (PMID 34113652, 2021).
juvenile dermatomyositis (1 paper, 2021). Juvenile dermatomyositis (JDM) is the early-onset form of dermatomyositis (DM), a systemic, autoimmune inflammatory muscle disorder, characterized by proximal muscle weakness, evocative skin lesion, and systemic manifestations. "Juvenile dermatomyositis (JDM) is the most common IIM in children, with an incidence of 3.2 per million children, positivity for anti-HMGCR and anti-SRP54 Ab were present in only 1–2.2 % of pediatric series from the UK and the USA with IIM." (PMID 34572153, 2021).
leukemia (1 paper, 2022). A malignant (clonal) hematologic disorder, involving hematopoietic stem cells and characterized by the presence of primitive or atypical myeloid or lymphoid cells in the bone marrow and the blood. "We describe our experience with the first reported case of leukemia in a patient with SRP54‐mutated CN." (PMID 35846055, 2022). "We report the first case of leukemia in a patient with SRP54‐mutated CN." (PMID 35846055, 2022). "Given the known risk of leukemia in other CNs it is crucial to know whether patients with SRP54‐mutated CN have an increased risk of leukemia." (PMID 35846055, 2022).
muscular atrophy (1 paper, 2021). The loss of muscle tissue due to inactivity or disease. "Muscular atrophy was significantly more present in SRP54-seropositive cases compared to HMGCR-positive patients, although it seems that a longer active disease period also leads to muscular atrophy in the latter group." (PMID 34572153, 2021). "This clinical aspect could also be observed in our patients, who both presented muscular atrophy at the last follow up, and, in the case of the anti-SRP54 positive patient, already early in the course of the disease." (PMID 34572153, 2021).
polymyositis (1 paper, 2006). A rare idiopathic inflammatory myopathy characterized by symmetric proximal muscle weakness and elevated muscle enzymes. "In an attempt to better characterize anti-SRP54 autoantibodies, we have identified SRP54 epitopes of the anti-SRP autoantibodies present in sera from polymyositis patients and investigated the effects of these autoantibodies on SRP functions in vitro." (PMID 16469117, 2006). "In the current article, we have characterized the specificity of anti-SRP54 autoantibodies, which are highly characteristic of polymyositis patients, and investigated the effect of these autoantibodies on the SRP function in vitro." (PMID 16469117, 2006).
infection (3 papers, 2021 to 2024). The state of being infected such as from the introduction of a foreign agent such as serum, vaccine, antigenic substance or organism. "In reported SRP54-positive cases, infection or coryzal illness preceded in more than half of the cases at the onset of muscular weakness." (PMID 34572153, 2021). "Collectively, these data imply that interaction of SRα with SRP54 via the NG-domain may be replaced by the viral non-structural proteins potentially for more efficient synthesis of the viral and selected host proteins during infection." (PMID 39621795, 2024). "Collectively, these results demonstrate ZIKV relies on SRP54 but not the SRP receptors SRα and SRβ for efficient propagation and membrane protein accumulation during infection." (PMID 39621795, 2024).
inflammatory myopathy (3 papers, 2015 to 2022). "Among all components of SRP, SRP54 is considered the main antigenic target of anti-SRP antibodies with antibodies against SRP54 found in patients with severe myopathies and Lupus-type autoimmune diseases." (PMID 34113652, 2021).
cancer (2 papers, 2021 to 2024). A tumor composed of atypical neoplastic, often pleomorphic cells that invade other tissues. "The same analysis conducted on TMA7, SPCS2, CDCP1, NT5C3A and SRP54 revealed a homogeneous expression in the majority of 33 TCGA histotypes of cancer." (PMID 33925480, 2021). "Polymorphisms were also found in other canonical cancer-related genes, including SLC37A3, BAZ1A, SRP54, MYH1 and ABCC1, but were not directly involved in MASLD pathogenesis." (PMID 38540416, 2024).
hematologic malignancies (1 paper, 2022). "SRP54 is one of at least 25 known genes implicated in CN, many of which have an increased risk of hematologic malignancies." (PMID 35846055, 2022). "None of these patients was transplanted for a hematologic malignancy and there have been no published reports of hematologic malignancies in patients with SRP54 mutations." (PMID 35846055, 2022).
neurodegenerative disease (1 paper, 2021). A disorder of the central nervous system characterized by gradual and progressive loss of neural tissue and neurologic function. "Both SRP54 and AGO2 have previously been implicated in neurodegenerative diseases; however, no such connections have been made with PD before our findings." (PMID 34685771, 2021).
SRP54 also shares sentences with these, for which no sentence is quoted: Cyclic neutropenia (2 papers); autoimmune hypophysitis (1); benign familial infantile seizures-5 (1); Duchenne muscular dystrophy (1); myasthenia gravis (1); Myelodysplasia (1); thyroiditis (1); ZIKV infection (1).